CYP27A1 (cytochrome P450 family 27 subfamily A member 1)
Diseases named in the same sentence as CYP27A1 in open-access papers (continued):
Sharing a sentence is not in itself a finding about the gene and the disease.
tumor (continued). "Particularly, not only is CYP27A1 abundant in macrophages, but it also catalyzes the conversion of cholesterol to 27-hydroxycholesterol (27HC), which promotes the growth of estrogen receptor-dependent tumor cells." (PMID 36685904, 2022). "Generally, patient and tumor characteristics had similar distributions between the overall cohort (n = 237) and the study-specific subset of patients (n = 193) who were evaluable for both CYP27A1 protein and mRNA expression." (PMID 34556659, 2021). "Notably, using the publicly available METABRIC and TCGA gene expression databases, we found that tumours that had high mRNA levels of CYP27A1 (and thus expected elevated 27OHC) also presented the increased expression of ER-β mRNA." (PMID 35011656, 2021). "The distributions of patients, tumor characteristics, and adjuvant treatment were compared between the overall populations and the subsets of patients with evaluable CYP27A1 expression within each cohort and were found to be well-balanced for the majority of factors assessed." (PMID 33176848, 2020). "Additional differences in patients, tumor characteristics, and molecular assays used for measuring the expression of CYP27A1 between the studies (protein vs mRNA) may also have contributed to these divergent results." (PMID 33176848, 2020). "For CYP27A1 negative tumours (n=367) the mean survival was 118 months (95% CI 108-128), for CYP27A1 weakly stained tumours (n=195) the mean survival was 108 months (95% CI 96-120) and for CYP27A1 moderately stained (n=44) tumours the mean survival was 91 months (95% CI 71-111)." (PMID 27341022, 2016). "Furthermore, analysis of the GSE13507 dataset revealed that six genes, LIMS2, IRAK3, STX2, CYP27A1, IL11RA, and KCNMB1, had AUC values greater than 0.7, demonstrating good diagnostic potential in differentiating healthy adjacent tissues from tumor samples." (PMID 40755754, 2025). "However, 27HC supplementation neutralized the inhibition of lung metastasis by DHCR7 knockdown, whereas the injection of the CYP27A1 inhibitor GW297X in cells overexpressing TMEM147 restrained tumor progression and metastasis, and supplementation with 27HC offset the effect of GW297X." (PMID 37891677, 2023). "The current research identified immune genes PLA2G2D, TNFAIP8L2, and CYP27A1 and immune cells-related pathways T cell receptor signaling, Th17 cell differentiation, and NK cell mediated cytotoxicity as the primary candidates involved in lipid metabolism-mediated tumor immunity in HNSC." (PMID 37210507, 2023). "Three immune genes (PLA2G2D, TNFAIP8L2, and CYP27A1) and immune-related pathways (T cell receptor signaling, Th17 cell differentiation, and natural killer (NK) cell mediated cytotoxicity) were predicted to play significant roles in the lipid metabolism-mediated tumor immunity in HNSC." (PMID 37210507, 2023). "CYP27A1 expression was not differentially associated with age, tumor size, ER, PgR, or HER2." (PMID 34556659, 2021). "Interestingly, in the case of TNBC, CYP27A1 expression is significantly upregulated in tumor samples compared to normal breast tissues, while CYP7B1 expression remains the same, suggesting a different regulatory mechanism in TNBC compared to ER-positive breast cancer." (PMID 32650428, 2020). "Notably, as Cyp27a1 is reported to be abundant in macrophages, these cells may also contribute to an increase in 27HC within the tumour microenvironment." (PMID 29371332, 2018). "Combined with the immune infiltration analysis, CYP27A1 expression was significantly positively correlated with the infiltration level of resting dendritic cells (r = 0.42, P = 0.001), implying that this gene may influence disease progression by modulating the tumor immune microenvironment." (PMID 40755754, 2025). "NAB2, CYP27A1, NPIPB4, MAOB, and SIAE, demonstrated lower expression for the OSCC group compared with a non-tumor group." (PMID 40723410, 2025).
tumor (continued). "To validate the expression levels of the eight key genes (LIMS2, TP53INP2, IRAK3, STX2, CYP27A1, IL11RA, KCNMB1, and PDLIM7) in tumor and non-tumor samples, we analyzed their expression in TCGA and GSE7476 datasets." (PMID 40755754, 2025). "We found that the mRNA expression CD68, CD69 and CYP27A1 levels were significantly downregulated, and PLTP levels was significantly up regulated in tumor samples." (PMID 37880277, 2023). "We show that OCDO, CT, and 5,6-ECs can be 27-hydroxylated by CYP27A1 and reveals a metabolic switching of the pro-tumor activity of OCDO to an anti-tumor activity in BC cells expressing CYP27A1 through the hydroxylation of OCDO at position C27." (PMID 37981011, 2023). "CYP27A1 was downregulated in HNSC tumor samples, while the other genes were upregulated in HNSC tumor samples A heatmap depicted the expression levels related to different clinical features." (PMID 37210507, 2023). "We investigated CYP27A1 and CYP7B1 protein expression in the tumor as markers indicative of local 27HC metabolism." (PMID 32075687, 2020). "MAOB, NPIPB4, CYP27A1, and SIAE showed significantly lower expression levels in OSCC tumor tissues compared to normal tissues." (PMID 31963366, 2020). "CELF5 was low-expressed in tumor cell line; AMACR, CYP27A1, CYP46A1, and CH25H were high-expressed in tumor cell line in CCLE." (PMID 32117422, 2019). "While down-regulation of genes such as CYP4A11, PLA2G4A, PLA2G3, LTC4S, CYP27A1, HMGCS2 and PDPK1 reduced patient overall survival time in most tumor types." (PMID 31074374, 2019). "of the Cancer Genome Atlas found that CYP27A1 expression was similar in normal breast and ER + tumours but CYP7B1 expression was decreased by 50% in ER + tumours compared with normal breast tissue." (PMID 29421651, 2018). "It has been reported that CYP27A1 and CYP27B1 were overexpressed in ovarian cancer cells, which can result in an increase in localized 1,25(OH)2D3 concentrations in the tumor and promote anticancer activity." (PMID 30157901, 2018). "That research highlighted the important roles played by the oxysterol metabolite 27-hydroxycholesterol which results from both anabolism and catabolism of CYP27A1 and CYP7B1 enzymes respectively in tumour pathophysiology." (PMID 27341022, 2016). "Additionally, elevated CYP27A1 expression has the potential to enhance antitumor immunity by attracting macrophages, CD8 T cells, B cells, NK cells, and Treg cells into the tumor microenvironment." (PMID 37817081, 2023). "Statistically significant expression changes were not noted in CYP7B1 and CYP27A1 between menopausal status and tumour grade." (PMID 37614064, 2023). "The distribution of positive/negative status for the tumor markers was comparable with distributions of ERβ, CYP27A1, and CYP7B1 previously reported." (PMID 32075687, 2020). "Interestingly, the mRNA levels of MAOB, NABNPIPB4, CYP27A1, and SIAE were lower in OSCC tumor tissues as compared to normal tissues, which is consistent with our results in the saliva samples." (PMID 31963366, 2020). "High CYP27A1 expression was more frequent among high-grade tumors lacking hormone receptor expression and with larger tumor sizes." (PMID 33176848, 2020). "The observed decrease is not due to an impaired bile acids synthesis by tumor cells, as the expression of the rate-limiting enzymes Cyp7a1 and Cyp27a1 was not affected in the transition from inflammation to tumors." (PMID 29734330, 2018). "Thirty-one tumor cell lines showed moderate to high expression of 27HC-generating enzyme CYP27A1 while none of the normal cell line showed moderate to high CYP27A1 expression." (PMID 30190703, 2018). "The mean survival in patients with tumours showing moderate/strong staining for CYP27A1 (n=60) was 82 months (95% CI 65-98) whereas for negative/weak tumours (n=562) the mean survival was 119 months (95% CI 110-127)." (PMID 27341022, 2016).
tumor (continued). "Furthermore, Cyp27a1−/− mice treated with AOM–DSS displayed more and larger tumours compared with their littermate controls and GW3965 administration in Cyp27a1−/− mice rescued this phenotype, suggesting that LXR activation downstream to CYP27A1 restrains intestinal tumorigenesis." (PMID 39567700, 2025). "Therefore, increasing CYP27A1 and CYP27B1 expression and decreasing CYP24A1 production may be beneficial for inhibiting tumor growth." (PMID 30157901, 2018). "Extending our findings to humans, we further confirmed downregulation of CYP27A1 in the colonic epithelium from patients with CRC compared with healthy individuals, suggesting that suppression of the CYP27A1–LXR axis might function as a tumour-escape mechanism." (PMID 39567700, 2025).
cancer (34 papers, 2010 to 2025). A tumor composed of atypical neoplastic, often pleomorphic cells that invade other tissues. "Intratumoral expression of CYP27A1 was linked to high grade cancer cells and ER-positive breast tumors." (PMID 33604295, 2020). "The current study confirms the anti-cancer properties of hydroxylumisterols with CYP27A1-derived (25R)-27(OH)L3 inhibiting proliferation of A375 and SK-MEL-28 cells." (PMID 39456696, 2024). "AKR1C1, CYP27A1, CYP2C9, GLB1, HMGCS2, and PLPP1, all six LMRGs, have been implicated in the genesis and progression of cancer." (PMID 36936948, 2023). "In contrast, the relationship between the expression of CYP27A1 in tumors and cancer prognosis has been inconsistent." (PMID 33604295, 2020). "CYP2R1, CYP27A1 and CYP3A4 are 3 major 25-hydroxylases responsible for the initial hydroxylation to convert vitamin D to 25 (OH)D, and their genetic polymorphisms have been found associated with different risks for developing certain types of cancer." (PMID 40630116, 2025). "This suggests that statins (which lower cholesterol) and inhibitors of CYP27A1 may become new cancer treatment strategies." (PMID 39574952, 2024). "Messenger RNAs encoded by CYP7B1 and CYP27A1 were detected in all cancer grades; expression of CYP7B1 was significantly lower in poorly differentiated cancers compared to moderately differentiated cancers (P < 0.05)." (PMID 29371332, 2018). "Ablation or inhibition of CYP27A1, the enzyme responsible for the rate-limiting step in 27-hydroxycholesterol biosynthesis, significantly reduces metastasis in relevant animal models of cancer." (PMID 29021522, 2017). "Thus, CYP27A1 functions as a cellular cholesterol sensor in cancer cells." (PMID 37508912, 2023). "In the present study, we evaluated whether OCDO and its precursors can undergo a 27-hydroxylation in cancer cells expressing CYP27A1 and compared the proliferative properties of 27H-OCDO ((25R)-cholestane-6-oxo-3β,5α,26-triol) on ER(+) and TN BC cells with OCDO and 27HC." (PMID 37981011, 2023). "EPHX2, ACSF2, CYP27A1, ACSS1, and ALDH1L1 showed hypermethylation in several types of human cancer; on the contrary, AKR1B10, POLG2, NDUFB8, ACACB, and MRPS22 consistently showed hypomethylation in several types of human cancer." (PMID 37223030, 2023). "Importantly, the effect of cyp27a1 inhibition on cancer may actually be advantageous, since we and others have shown that 27HC promotes the progression of a variety of cancers, and cyp27a1 inhibition had favorable impact on a preclinical model of breast cancer." (PMID 37491347, 2023). "Relative expression of CYP27A1 tended to be higher in poorly differentiated cancers, but this was not significant." (PMID 29371332, 2018). "Besides, ablation of cytochrome P450 family 27 subfamily A member 1 (CYP27A1), a rate-limiting enzyme responsible for 27-hydroxycholesterol biosynthesis, could dramatically inhibit metastasis of cancers by decreasing the amount of CD8+ T cells." (PMID 35720273, 2022). "As concentrations of CYP7B1 mRNAs were significantly decreased in poorly compared to moderately differentiated cancers and expression of CYP27A1 did not change significantly across EC grades; we believe this would favour increased bioavailability of 27HC with increasing grade." (PMID 29371332, 2018).
infection (12 papers, 2006 to 2025). The state of being infected such as from the introduction of a foreign agent such as serum, vaccine, antigenic substance or organism. "In contrast, the mRNA and protein levels of hepatic CYP7B1, CYP8B1, and CYP27A1 were all increased by Ad-378 infection and decreased by Ant-378 administration, respectively." (PMID 33754066, 2021). "We thus determined whether infection with the S. Typhimurium wild type decreased expression of genes involved in bile acid synthesis, including Cyp7a1, Cyp8b1, Cyp27a1, and Cyp7b1." (PMID 40938708, 2025). "The upregulation of CYP27A1 could be attributed to the control of excessive cholesterol biosynthesis at the late stage of in vitro infection." (PMID 37631994, 2023). "Similar results were obtained in primary murine hepatocytes after Ad-378 infection or Ant-378 transfection, suggesting that miR-378 regulates hepatic CYP7B1, CYP8B1, and CYP27A1 expression in a cell-autonomous manner." (PMID 33754066, 2021). "Since synthetic agomir for miR-378* (AgomiR-378*) transfection could not affect the mRNA expression of CYP7B1, CYP8B1, and CYP27A1, we speculated that miR-378 but not miR-378* contributes to the effect of Ad-378 infection on the expression of these enzymes." (PMID 33754066, 2021).
genetic disorder (5 papers, 2022 to 2024). "Cerebrotendinous xanthomathosis constitutes a rare genetic disorder associated with the CYP27A1 mutation." (PMID 38952472, 2024).
autosomal recessive disease (4 papers, 2010 to 2023). Autosomal recessive form of disease. "This autosomal recessive disease is caused by pathogenic variants in CYP27A1, which codes sterol 27-hydroxylase, an enzyme of the cytochrome P450 oxidase system with an important role in cholesterol metabolism and bile acid synthesis." (PMID 37508912, 2023).
metabolic disease (4 papers, 2024 to 2026). A congenital disorder (due to inherited enzyme abnormality) or acquired (due to failure of a metabolically important organ) disorder resulting from an abnormal metabolic process. "CTX is a metabolic disorder caused by pathogenic variants in the CYP27A1 gene, which encodes the sterol 27-hydroxylase enzyme." (PMID 39595922, 2024).
Cardiovascular Disease (2 papers, 2015 to 2025). "In the present study, we analyzed the CYP2R1, CYP27A1, and CYP27B1 genetic polymorphisms and their association with anthropometric parameters, concentrations of 25(OH)D2, 25(OH)D3, 3-epi-25(OH)D2, 3-epi-25(OH)D3, and 1,25(OH)2D3, in Polish patients with cardiovascular disease and healthy subjects." (PMID 40427592, 2025).
kidney (2 papers, 2021 to 2023). "This study examined the association between CYP27A1 expression and prognosis in a cohort of 193 premenopausal patients with lymph node-negative primary BC with limited exposure to adjuvant systemic cancer treatments." (PMID 34556659, 2021).
neurological disease (2 papers, 2022 to 2023). "Impaired cholesterol homeostasis in the CNS contributes to neurological disorders such as CTX and SPG5, which are caused by biallelic mutations in the CYP27A1 and CYP7B1 genes, respectively." (PMID 37024986, 2023). "Unfortunately, the remaining four patients with moderate elevations of cholestanol levels, who had normal cholestanol/cholesterol ratios (1.99–2.28) and no personal or family history of neurological disease nor chronic diarrhea, did not undergo CYP27A1 sequencing." (PMID 36514115, 2022).
peripheral neuropathy (2 papers, 2023 to 2024). A disorder affecting the peripheral nervous system. "Notably, a novel variant (c.670_671delAA) in CYP27A1 gene was identified in three patients who also presented with peripheral neuropathy and bilateral pes cavus." (PMID 38336741, 2024).
adenocarcinoma (1 paper, 2023). A common cancer characterized by the presence of malignant glandular cells. "Significant upregulation of TNFAIP6 and TLR6 and downregulation of P2RY13 and CYP27A1 were observed in all three adenocarcinoma cell lines." (PMID 38204755, 2023).
neurodegenerative disease (1 paper, 2017). A disorder of the central nervous system characterized by gradual and progressive loss of neural tissue and neurologic function. "Because ALS is a neurodegenerative disease, we speculated that, when cholesterol is released by neurons as they die, it would be metabolized by CYP46A1 to 24S-hydroxycholesterol (24S-HC) and by CYP27A1 to members of the acidic pathway of bile acid biosynthesis (respectively)." (PMID 27811233, 2017).
CYP27A1 also shares sentences with these, for which no sentence is quoted: Cognitive impairment (4 papers); Ataxia (3); bladder (3); cognitive decline (3); COVID-19 (3); Osteopenia (3); anemia (2); coronary artery disease (2); eczema (2); endometrial carcinoma (2); epilepsy (2); Hypertension (2); hypogonadism (2); Infertility (2); non-small cell lung carcinoma (2); Parkinsonism (2); prostate adenocarcinoma (2); thrombosis (2); Viral infection (2); 22q11.2 deletion syndrome (1); alcohol (1); allergic rhinitis (1); Anorexia (1); apraxia (1); Arthritis (1); autoimmune disease (1); bacterial infection (1); behavioral variant frontotemporal dementia (1); bile acid synthesis (1); bladder urothelial carcinoma (1).
A further 69 diseases each share a sentence with CYP27A1 in 1 paper.